BATF2 (basic leucine zipper ATF-like transcription factor 2)
Description:
AP-1 family transcription factor that controls the differentiation of lineage-specific cells in the immune system. Following infection, participates in the differentiation of CD8(+) thymic conventional dendritic cells in the immune system. Acts via the formation of a heterodimer with JUN family proteins that recognizes and binds DNA sequence 5'-TGA[CG]TCA-3' and regulates expression of target genes (By similarity). Selectively suppresses CCN1 transcription and hence blocks the downstream cell proliferation signals produced by CCN1 and inhibits CCN1-induced anchorage-independent growth and invasion in several cancer types, such as breast cancer, malignant glioma and metastatic melanoma. Possibly acts by interfering with AP-1 binding to CCN1 promoter.
Synonyms: SARI; MGC20410
Tractability: No criterion of Open Targets' tractability assessment is met for any kind of drug.
Gene: Protein-coding gene on chromosome 11 (64,987,945 to 64,997,018, reverse strand). Ensembl gene ENSG00000168062.
Subcellular location: Nucleus
Subcellular location (Human Protein Atlas): Nucleoli
Gene Ontology:
Molecular function: protein binding; DNA-binding transcription factor activity, RNA polymerase II-specific; RNA polymerase II cis-regulatory region sequence-specific DNA binding; DNA binding; DNA-binding transcription factor activity
Biological process: defense response to protozoan; integrated stress response signaling; myeloid dendritic cell differentiation; regulation of transcription by RNA polymerase II; regulation of DNA-templated transcription
Cellular component: RNA polymerase II transcription regulator complex; chromatin; nucleus
Genetic constraint (gnomAD): Loss-of-function variants: 5 observed, 6.75 expected, observed/expected ratio (o/e) 0.74, 90% interval 0.38 to 1.52. That is too few expected variants to judge how well the gene tolerates losing a copy. Missense variants: 295 observed, 338.15 expected, observed/expected ratio (o/e) 0.87, 90% interval 0.79 to 0.96. Synonymous variants: 152 observed, 154.04 expected, observed/expected ratio (o/e) 0.99, 90% interval 0.86 to 1.13.
Homologues: Orthologues: chimpanzee BATF2 (98% identical), macaque BATF2 (91% identical), pig BATF2 (70% identical), dog BATF2 (65% identical), rabbit BATF2 (64% identical), mouse Batf2 (62% identical), rat Batf2 (60% identical), guinea pig BATF2 (58% identical), Drosophila melanogaster Atf3 (24% identical), zebrafish fosaa (18% identical), zebrafish si:ch211-153j24.3 (13% identical). Paralogues in human: FOSB (18% identical), BATF (16% identical), BATF3 (16% identical), FOS (16% identical), FOSL2 (15% identical), FOSL1 (15% identical), JDP2 (11% identical), ATF3 (10% identical).
Diseases named in the same sentence as BATF2 in open-access papers:
BATF2 is named in the same sentence as 74 diseases in open-access papers, as found by Europe PMC text mining. Sharing a sentence is not in itself a finding about the gene and the disease. The quoted sentences say what the papers report.
gastric cancer (24 papers, 2020 to 2025). A primary or metastatic malignant neoplasm involving the stomach. "To investigate BATF2's influence on the stem-like characteristics of gastric cancer cells, we assessed the presence of stem cell-associated markers in both traditional adherent cell cultures and 3D tumor spheroids." (PMID 39629124, 2024). "This reduction underscores BATF2's significant role in controlling the proliferation of gastric cancer organoids." (PMID 39629124, 2024). "This study expands on BATF2's role in gastric cancer, demonstrating how it interacts with PTEN to suppress the AKT/β-catenin/ABCG2 signaling pathway, impacting stem cell markers like ABCG2, CD44, SOX2, and NANOG, based on in vivo and in vitro analyses." (PMID 39629124, 2024). "Our data suggests that by downregulating ABCG2, BATF2 can potentially amplify the chemotherapeutic responsiveness of gastric cancer cells, offering a promising avenue for enhancing treatment efficacy." (PMID 39629124, 2024). "In gastric cancer, BATF2 mediated by mA modification can suppress tumor through the inhibition of ERK signaling." (PMID 38206646, 2024). "Specifically, gastric cancer cells with enhanced BATF2 expression exhibited significantly lower levels of the cancer stem cell markers CD44, NANOG, and SOX2 than the control cells." (PMID 39629124, 2024). "When gastric cancer organoids were infected with the BATF2-expressing letiviruses, there was a notable decline in both the count and size of these organoids after 14 days, compared to the control group." (PMID 39629124, 2024). "In our cellular studies, gastric cancer cells with increased BATF2 expression had a lower IC50 value for 5-Fu, suggesting a heightened sensitivity to the chemotherapy compared to control cells." (PMID 39629124, 2024). "To further explore BATF2's role in modulating stem-like characteristics of gastric cancer cells in a live organism, we developed tumor xenograft models using various cell counts of BATF2-overexpressing and control cells." (PMID 39629124, 2024). "Our findings align with previous chemotherapy data, suggesting BATF2's role in enhancing gastric cancer cells' responsiveness to 5-Fu." (PMID 39629124, 2024). "Collectively, these results illustrate that BATF2 knockdown amplifies gastric cancer stem cell-like properties by upregulating the AKT pathway and its associated stemness-related genes." (PMID 39629124, 2024). "To examine the specific expression levels of BATF2 in human gastric cancer specimens, we incorporated nine samples into our single-cell RNA sequencing (scRNA-seq) study." (PMID 39629124, 2024). "This pattern indicates that gastric cancer cells with high BATF2 levels exhibit increased vulnerability to chemotherapy, while those surviving tend to resist drugs, as indicated by heightened ABCG2 levels." (PMID 39629124, 2024). "Despite these insights, the relationship between BATF2 and the stem-like traits and chemotherapy resistance in gastric cancer remains underexplored." (PMID 39629124, 2024). "BATF2 has been reported as an independent prognostic factor in gastric cancer patients, and high BATF2 expression significantly suppressed gastric cancer growth and metastasis." (PMID 37777155, 2023). "Among other cancers, BATF2 was demonstrated as a tumor suppressor of gastric cancer, glioblastoma, and esophageal squamous cell carcinoma." (PMID 36077244, 2022). "For example, METTL3-mediated m6A modification destabilizes SOCS2 mRNA in HCC and BATF2 mRNA in gastric cancer and promotes the translation of epidermal growth factor receptor (EGFR) and the Hippo pathway effector TAZ in human lung cancer cells." (PMID 35456475, 2022). "For example, aberrant m6A modifications of BATF2 mRNA by METTL3 repressed its expression in gastric cancer, which contributes to the tumor growth and metastasis." (PMID 33726814, 2021).
gastric cancer (continued). "Moreover, in other tumors such as hepatocellular carcinoma (HCC), non-small-cell lung cancer (NSCLC), esophageal squamous cell carcinoma (ESCC) and gastric cancer (GC), the down-regulation of BATF-2 expression is associated with a poor prognosis." (PMID 34565331, 2021). "Furthermore, within our center's gastric cancer cohort, there were 250 instances of low BATF2 expression versus 95 cases with high expression." (PMID 39629124, 2024). "Besides, it has been reported that miRNA-765 mediated multidrug resistance (MDR) via targeting BATF2 in gastric cancer cells." (PMID 38420020, 2024). "We hypothesized that BATF2 inhibits stem-like properties of gastric cancer cells via AKT signaling pathway." (PMID 39629124, 2024). "To explore how BATF2 heightens the responsiveness of gastric cancer cells to 5-Fu therapy, we performed whole-transcriptome sequencing which suggested a link between BATF2 and the ATP-binding cassette transporter, pinpointing ABCG2 as a key downstream target influenced by BATF2." (PMID 39629124, 2024). "BATF2, a tumor suppressor, is known for its role in gastric cancer, but its influence on cancer stem cell-like properties and chemotherapy response remains unclear." (PMID 39629124, 2024). "Here, we established an activated CD4+ memory T cells-related 3-gene prognostic model (BATF2, MYB and CD36) in gastric cancer to evaluate the activation status of CD4+ memory T cells." (PMID 37781029, 2023). "In gastric cancer, m6A modification activated the ERK pathway by inhibiting BATF2." (PMID 37095108, 2023). "The cytoplasmic localisation of BATF2 was observed in multiple tumours, including CRC, liver cancer, bile duct cancer, gastric cancer, kidney cancer, lung adenocarcinoma, lung adenosquamous carcinoma, lung squamous cell carcinoma, nasopharyngeal carcinoma and pancreatic adenocarcinoma." (PMID 37151195, 2023). "In this study, five crucial immunophenotype‐related molecules (WARS, UBE2L6, GZMB, BATF2, and LAG‐3) in the TME are determined in five public gastric cancer (GC) datasets (n = 1426) and an in‐house sequencing dataset (n = 79)." (PMID 36998102, 2023).
tuberculosis (10 papers, 2015 to 2022). A chronic, recurrent infection caused by the bacterium Mycobacterium tuberculosis. "We show that a single transcript (BATF2) and seven other multi-transcript signatures, regulated by interferon signalling, perform with equivalent diagnostic accuracy for incipient tuberculosis." (PMID 31958400, 2020). "In summary, we show for the first time that eight transcriptional signatures, including a single transcript (BATF2), have equivalent diagnostic accuracy for identification of incipient tuberculosis." (PMID 31958400, 2020). "In their study, BATF2, an active TB-derived biomarker, was used to identify cases of incipient tuberculosis among TB-progressors from Zak's cohort, with promising results." (PMID 32760401, 2020). "The signature with the largest AUC for the identification of incipient tuberculosis over a 2-year period tested in pooled data from all 1126 samples was BATF2 (AUC 0·74, 95% CI 0·69–0·78)." (PMID 31958400, 2020). "BATF2 has been identified to be one of the biomarkers that can predict the progression of active tuberculosis for individuals who have close contact with tuberculosis patients." (PMID 32849329, 2020). "Using human whole blood transcriptomics, we identified elevated expression of BATF2 as an early correlate for tuberculosis (TB) disease progression in adolescents with latent Mycobacterium tuberculosis (Mtb) infection." (PMID 30542107, 2019). "We currently started infection studies in Batf2 deficient mice, and depending on the biological outcome, Batf2 might be an interesting biomarker and possible candidate for host directed therapy against tuberculosis (TB)." (PMID 26376615, 2015). "We suggest to include Batf2 in the search of new targets for host-directed drug therapies against tuberculosis due to its important regulation of inflammation and macrophage killing effector functions and its specific expression to macrophage/DC cells, the primary target cells of Mtb." (PMID 26376615, 2015). "Blood BATF2 transcripts provide a single biomarker for active tuberculosis and a novel four-gene transcriptional signature differentiates active TB from other infectious diseases with fever." (PMID 27734027, 2016). "Hence, Batf2 could be used as a biomarker and a potential host directed drug target in tuberculosis." (PMID 26376615, 2015). "A meta-analysis performed with 16 microarray datasets to profile the host transcriptional response in active tuberculosis led to the identification of five upregulated genes: AIM2, BATF2, FCGR1B, HP, and TLR5." (PMID 35456421, 2022). "Here, we show that absence of Batf2 could dampen over-inflamed immunological state leading to resistance against tuberculosis and listeriosis in mice." (PMID 30542107, 2019).
colorectal cancer (9 papers, 2015 to 2025). A primary or metastatic malignant neoplasm that affects the colon or rectum. "Upregulation of BATF2 inhibited human colorectal cancer cells' growth and epithelial-mesenchymal transformation." (PMID 34868310, 2021). "BATF2-negative colorectal cancer patients exhibited poorly differentiated cancer cells alongside deeper invasion, higher TNM stage, and shorter survival post-surgery versus BATF2-positive colorectal cancer cases." (PMID 34778372, 2021). "Abnormalities in BATF-2 and cellular communication network factor 1 (CCN1) expressions and their correlation are closely associated with malignant behaviors of colorectal cancer cells, affecting the prognosis of patients." (PMID 34565331, 2021). "We have also found that repressing the nuclear export of BATF2 by mutating its nuclear export sequence and suppressing the expression of chromosome region maintenance 1 (CRM1) might serve as potential therapeutic approaches for patients with colorectal cancer." (PMID 38420020, 2024).
hepatocellular carcinoma (6 papers, 2015 to 2024). A malignant tumor that arises from hepatocytes. "BATF2 has been reported as a tumor suppressor gene in various malignant tumors, such as lung cancer, prostate cancer, colorectal carcinoma, hepatocellular carcinoma, and nasopharyngeal carcinoma, etc." (PMID 34778372, 2021). "Low BATF2 expression may increase the risk of hepatocellular carcinoma (HCC) development and has a significant association with a poor prognosis." (PMID 34778372, 2021). "Further investigation into BATF2 dysfunction revealed no mutations in the exons of the BATF2 gene in hepatocellular carcinoma." (PMID 38420020, 2024).
colon cancer (5 papers, 2020 to 2024). "Similarly, in colon cancer, BATF2 was found to be downregulated, and high BATF2 was related with epithelial-to mesenchymal (EMT) transition." (PMID 37777155, 2023). "Ceruloplasmin is a direct target of SARI (basic leucine zipper ATF-like transcription factor 2) in dextran sodium sulfate (DSS)- and azoxymethane (AOM)-induced colon cancer." (PMID 34413268, 2021). "Statistical analysis showed a significantly negative correlation between miR-939-3p and BATF2 expression levels in both sarcoma tissues (r = -0.8600, P = 0.0003) and colon cancer tissues (r = -0.7162, P = 0.0088), implying the involvement of a potential miR-939-3p/BATF2 signaling pathway in sarcoma." (PMID 38420020, 2024).
glioblastoma (5 papers, 2019 to 2025). The most malignant astrocytic tumor (WHO grade IV). "In this study, we demonstrate that loss of BATF2 does increase the expression of proliferation markers in Batf2−/− astrocytes; however, this effect was observed in otherwise normal cells that lack many of the genetic mutations detected in glioblastoma." (PMID 40945729, 2025). "In addition, we examined the relationship of BATF2 and cyclin D1 in patient-derived glioblastoma samples and found that elevated levels of BATF2 had a corresponding decrease in cyclin D1." (PMID 40945729, 2025). "Interestingly, EVs derived from glioblastoma that contain basic leucine zipper ATF-like transcription factor 2 (BATF2) have been discovered to inhibit the chemotaxis and recruitment of MDSCs, thus preventing the formation of an immunosuppressive microenvironment typically sculpted by MDSCs." (PMID 38816455, 2024). "We also evaluated BATF2 and cyclin D1 expression within glioblastoma multiforme (GBM) patient samples to assess if a similar relationship may exist in disease." (PMID 40945729, 2025).
lung adenocarcinoma (5 papers, 2012 to 2023). A carcinoma that arises from the lung and is characterized by the presence of malignant glandular epithelial cells. "Loss of SARI (suppressor of AP-1, also called BATF2) expression initiates EMT, causing repression of E-cadherin and upregulation of vimentin in lung adenocarcinoma cell lines and in human lung adenocarcinomas." (PMID 27018053, 2016).
sarcoidosis (5 papers, 2019 to 2023). Sarcoidosis is a multisystemic disorder of unknown cause characterized by the formation of immune granulomas in involved organs. "Enriched genes including MPO (myeloperoxidase), CXCL11, IL1A, CXCL10, FCGR3B, IL1B, TTN (titin), BATF2, VIP (vasoactive intestinal peptide), TLR3, CCR2, TLR7, and CR1 wereclosely related to sarcoidosis." (PMID 38137330, 2023). "Comparing to other infections or inflammatory conditions, human whole blood BATF2 expression was significantly increased in patients with Influenza A, B, rhinovirus infection (Public US Cohort GSE 68310) and sarcoidosis (Public UK Cohort GSE 42826) when compared to healthy controls." (PMID 30542107, 2019).
viral infection (4 papers, 2015 to 2023). "We found a nearly perfect antisense complementarity for the entire CoV2‐miR‐O7a.2 sequence to the 3′ untranslated regions (3′UTR) of BATF2 with 100% complementarity in the seed region, which is a transcription factor that plays a major role in innate immunity during viral infection." (PMID 34914162, 2022). "Since Batf2 is induced by type I IFNs, one could speculate that Batf2 may play a fundamental role during viral infection including HIV, however no studies investigated this hypothesis so far." (PMID 26376615, 2015).
breast carcinoma (3 papers, 2021 to 2024). "Herein, we aimed to explore the expression pattern and clinical implications of BATF2 in breast cancer (BC)." (PMID 34565331, 2021). "The role of LRFN4, BATF2, and HGSNAT in breast cancer remains unexplored." (PMID 39720180, 2024). "Generally, BATF2 mRNA exhibited a non-significant association with BC prognosis; yet the subgroup analyses showed that triple-negative breast cancer (TNBC) patients with high BATF2 mRNA expressions had a longer overall survival (OS)." (PMID 34565331, 2021).
colitis (3 papers, 2019 to 2023). Inflammation of the colon. "Mechanistic studies revealed that the protective effect of MANF against colitis is associated with CHOP/BATF2-mediated regulation of inflammation in macrophages." (PMID 36635421, 2023). "Batf2 deficiency in mice resulted in the development of spontaneous colitis and ileitis." (PMID 30753547, 2019). "In this study, we identified alterations in the fecal microbiota composition of Batf2−/− mice with spontaneous colitis and ileitis, such as increased Bacilli and Epsilonproteobacteria and reduced Erysipelotrichia." (PMID 30753547, 2019). "Batf2−/− mice spontaneously developed colitis and ileitis with altered microbiota composition." (PMID 30753547, 2019). "Therefore, MANF negatively regulates the expression of BATF2-mediated proinflammatory cytokines and chemokines in colonic macrophages, which may account for its role in controlling colitis." (PMID 36635421, 2023). "Thus, BATF2 is required for the inhibition of spontaneous colitis accompanied with dysbiosis." (PMID 30753547, 2019). "Moreover, the infiltration of inflammatory cells was increased in the ileum of Batf2−/− mice, indicating that the lack of BATF2 resulted in the development of spontaneous colitis and ileitis." (PMID 30753547, 2019).